DNAJB6 (DnaJ heat shock protein family (Hsp40) member B6)
Diseases named in the same sentence as DNAJB6 in open-access papers (continued):
Sharing a sentence is not in itself a finding about the gene and the disease.
amyloid (2 papers, 2018 to 2022). "Our work provides insight into how human DnaJB6 counteracts cellular toxicity caused by amyloid and establishes an in vivo genetic system useful for studying DnaJB6-amyloid interactions to decipher its mechanisms of action." (PMID 36552355, 2022). "This difference reveals limitations of DnaJB6 that have implications regarding its therapeutic use for amyloid disease." (PMID 36552355, 2022). "The structure of the oligomer and the S/T-rich region is of great importance for the understanding of the function of DNAJB6 and how it can bind aggregation-prone peptides and prevent amyloid diseases." (PMID 29581438, 2018). "This limitation raises concerns about developing DnaJB6 as a therapeutic for amyloid diseases." (PMID 36552355, 2022). "Together, these findings imply that DNAJB6 can be used as a tool to facilitate the understanding of the aggregation process and its inhibition, as well as in the development of future treatment of amyloid diseases." (PMID 29581438, 2018).
Ataxia (2 papers, 2017 to 2021). Ataxia refers to impaired coordination of voluntary muscle movement. "DNAJB6 works at the level of formation of polyQ oligomers independent of the context flanking the polyQ region, and thus its use can be extrapolated to other polyQ disorders such as spinocerebellar ataxia, spinal and bulbar muscular atrophy, and dentatorubropallidoluysian atrophy." (PMID 34755099, 2021).
atherosclerosis (2 papers, 2012 to 2022). A disease characterized by the build-up of fatty material and calcium deposition in the arterial wall resulting in partial or complete occlusion of the arterial lumen. "The biological function and their roles in atherosclerosis progression for the other genes, including DAZAP2, ARL6ip, CDK7, LIMS, HBP1, and DNAJB6, remain to be investigated." (PMID 35795669, 2022). "Several of the differentially regulated genes are involved in vascular pathophysiology; for example: DNAJB6 and DUSP1 (atherosclerosis), NAMPT (vascular inflammation), FCAR (myocardial infarction), IL8 (vascular remodelling), FFAR2 (lipid metabolism) and SOD2 (idiopathic cardiomyopathy (IDC))." (PMID 22409835, 2012).
Autosomal dominant limb-girdle muscular dystrophy type 1D (2 papers, 2016 to 2017). Autosomal dominant limb-girdle muscular dystrophy type 1D (LGMD1D) is a limb girdle muscular dystrophy (LGMD ; see this term) characterized by muscular weakness, primarily affecting the pelvic and shoulder girdles with no bulbar weakness or dysarthria. "One of the HSP40 proteins, DNAJB6, was discovered as the causative gene of the limb-girdle muscular dystrophy type 1E." (PMID 28845464, 2017). "Mutations in the DNAJB6 gene have been associated with the autosomal dominant limb girdle muscular dystrophy type 1D (LGMD1D), a disorder characterized by abnormal protein aggregates and rimmed vacuoles in muscle fibers." (PMID 27747217, 2016).
colorectal cancer (2 papers, 2019 to 2022). A primary or metastatic malignant neoplasm that affects the colon or rectum. "The CNV gain in the 7q36.3 in tumor 688 covers the DNAJB6 which has been implicated for its oncogenetic role in promoting cell invasion in colorectal cancer." (PMID 30975103, 2019).
esophageal cancer (2 papers, 2022 to 2024). A primary or metastatic malignant neoplasm involving the esophagus. "Accordingly, they proposed for the first time compelling evidence that overexpression of DNAJB6 increased ferroptosis in esophageal cancer cells by down-regulating GPX4." (PMID 36237575, 2022).
synucleinopathies (2 papers, 2022 to 2024). "Our results suggest that therapeutic efforts to target the activity of DNAJB6 and related co-chaperones in synucleinopathies and poly-Q disorders may also be beneficial for c9FTD/ALS patients, potentially targeting both TDP-43 and poly-GA aggregation." (PMID 35164882, 2022).
astrocytic tumor (1 paper, 2017). A glial tumor of the brain or spinal cord showing astrocytic differentiation. "Therefore, to gain more mechanistic insight into the role of DNAJB6(S), we explored the cytoprotection of DNAJB6(S) against MPP+-induced apoptosis and the molecular mechanisms underlying this process in cultured LN18 cells from astrocytic tumors." (PMID 28280525, 2017).
Bethlem myopathy (1 paper, 2022). A usually autosomal dominant inherited movement disorder caused by mutations in the COL6A1, COL6A2, and COL6A3 genes. "Autosomal dominant LGMDs represent about 10–15% of LGMDs and include disorders due to defects of DNAJB6, transportin-3 (TNPO3), HNRNPDL, Calpain-3 (CAPN3), and Bethlem myopathy." (PMID 35309568, 2022).
breast tumor (1 paper, 2021). "DnaJB6 is a negative regulator of breast tumor formation and metastasis." (PMID 33747911, 2021).
desminopathies (1 paper, 2025). "Our data delineate a pathogenetic link between the myeloid leukaemia factors 1 and 2 and the myofibrillar myopathy– and protein quality control‐related proteins Dnajb6 and Bag3 in the context of desminopathies." (PMID 41165044, 2025). "Notably, Mlf2, an interaction partner of Mlf1, has been shown be enriched in protein aggregates in human desminopathies thus highlighting a novel and conceivable disease link between Mlf1 and Mlf2 related transcriptional control and Dnajb6 and Bag3 mediated protein quality control." (PMID 41165044, 2025).
distal myopathy (1 paper, 2020). Distal myopathy refers to a group of muscle diseases which share the clinical pattern of predominant weakness and atrophy beginning in the feet and/or hands. "Recently, novel mutations located within a 7 amino acid region of the DNAJB6 J domain have been reported to cause dominant distal myopathy." (PMID 32497100, 2020).
Dystroglycanopathies (1 paper, 2022). "Mutations in DNAJB6 are found in LGMDD1 (OMIM: 603511) where a proportion of patients suffer from facial weakness and respiratory disability, resembling clinical features of LGMD/Dystroglycanopathies." (PMID 34740639, 2022).
glioblastoma (1 paper, 2021). The most malignant astrocytic tumor (WHO grade IV). "In addition, the overexpression of DNAJB6 leads to radiosensitization of glioblastoma cells." (PMID 33594759, 2021).
HCMV infection (1 paper, 2012). "The second set of experiments was to determine if the native (untagged) UL70 protein is associated with DNAJB6 in human cells during HCMV infection." (PMID 23133382, 2012). "Further experiments in fibroblasts and other cells permissive to HCMV infection should elucidate the role of DNAJB6 in these cells." (PMID 23133382, 2012). "Two sets of experiments were further carried out to determine if UL70 specifically interacts with endogenous DNAJB6 in human cells and in the presence of HCMV infection." (PMID 23133382, 2012). "To determine the effect of altered expression of DNAJB6 on HCMV infection, we examined the profiles of viral gene expression by assaying the production of viral proteins of different kinetic classes during replication in cells where the expression of DNAJB6 had been altered." (PMID 23133382, 2012). "Furthermore, the roles of DNAJB6 in UL70 localization and HCMV infection were investigated using U251 cells." (PMID 23133382, 2012).
lung adenocarcinoma (1 paper, 2024). A carcinoma that arises from the lung and is characterized by the presence of malignant glandular epithelial cells. "We explored the effect of DNAJB6 expression on the prognosis of patients and its biological role in lung adenocarcinoma (LUAD)." (PMID 39335495, 2024).
motor neuron degeneration (1 paper, 2023). "In fact, mutations in genes coding for several HSPs (e.g., HSPB1, HSPB3, HSPB8 and DNAJB6) are causative not only for myopathies, but also for distal hereditary peripheral neuropathies, which are characterized by motor neuron degeneration." (PMID 40757567, 2023).
muscular disease (1 paper, 2017). Myopathy is a peripheral nervous system disease consisting of any abnormal condition or disease of the muscular tissues; commonly designates a disorder involving skeletal muscle. "Conversely, mutations in small HSPs such as HSPB1, HSPB3, HSPB5, HSPB8 and the co-chaperones DNAJB6 and BAG3 have all been associated with motor neuron and muscular diseases." (PMID 28396624, 2017).
neuroblastoma (1 paper, 2023). Neuroblastoma (NB) is the most common solid, extracranial childhood tumor. "Together, these results suggest that DNAJB6 may untangle tau aggregation in human neuroblastoma cells." (PMID 38110916, 2023). "Since we found that DNAJB6 can decrease tau aggregation in human neuroblastoma cells, we would like to know whether tau, the client, is associated with HSPA8-DNAJB6, the chaperone–cochaperone complex." (PMID 38110916, 2023).
protein (1 paper, 2025). "Limb-girdle muscular dystrophy D1 (LGMDD1) is a rare, dominantly inherited neuromuscular protein-misfolding chaperonopathy caused by mutations in the Hsp40 co-chaperone DNAJB6, primarily in the glycine-phenylalanine (GF) or J-domains." (PMID 41241098, 2025).
Skeletal myopathy (1 paper, 2024). "Numerous studies have identified DNAJB6 mutations as a cause of skeletal myopathy however, the function of DNAJB6 in the muscle is still unclear." (PMID 38621658, 2024). "To determine the underlying cause of muscle weakness we considered the role of autophagy, as mutation of DNAJB6 has previously been associated with autophagic defects and defects in autophagy are a known cause of skeletal myopathy." (PMID 38621658, 2024).
type 2 diabetes (1 paper, 2021). "However, the exact association between DNAJB6 and type 2 diabetes needs further study." (PMID 34650136, 2021).
myopathies (22 papers, 2013 to 2025). "Herein, we employed functional assays along with advanced molecular simulation studies to understand the regulatory interdomain interactions in disease-causing mutants of DNAJB6 that cause LGMDD1 myopathy." (PMID 41241098, 2025). "We previously reported that pathogenic variants in both DNAJB4 and its homolog DNAJB6, which are associated with myopathy, alter the aggregation and disaggregation of their putative client protein, TDP-43." (PMID 39468638, 2024). "This rare mutation type expands the molecular spectrum of DNAJB6-myopathy and further underlines the importance of the G/F region." (PMID 35812750, 2022). "In recent years, the phenotypic and molecular spectrum of DNAJB6-myopathy has been expanded, and several mutations of DNAJB6 have been identified in Europe, North America, and Asia." (PMID 35812750, 2022). "Dominant mutations within DNAJB6 (Hsp40)—an Hsp70 co-chaperone—lead to a protein aggregation-linked myopathy termed Limb-Girdle Muscular Dystrophy Type D1 (LGMDD1)." (PMID 35931773, 2022). "Taking together, these findings reveal the pathogenic role of DNAJB6a insufficiency in myofibrillar myopathies and expand upon the molecular spectrum of DNAJB6 mutations." (PMID 33557929, 2021). "LGMDD1 is a myopathy historically characterized by mutations within the G/F domain of the chaperone DNAJB6." (PMID 32497100, 2020). "In the present review we will focus our attention on the pathological effects of mutations affecting the DNAJB6 chaperone protein, and on the clinical and histopathological features of the DNAJB6-related myopathies." (PMID 27747217, 2016). "The current, and potentially future, mutations in DNAJB6-myopathy patients will be crucial guides in obtaining this knowledge." (PMID 26205529, 2015). "In summary, it appears that the range of severity in DNAJB6 myopathy in presently known mutations is as follows: ΔG/F and Phe91 mutations, most severe – Phe100Val, Pro96Arg and Phe89 mutations, intermediate severity – Phe93 mutations, least severe." (PMID 26205529, 2015). "Functional insights – Evidence strongly suggests that DNAJB6-myopathy mutations are gain-of-deleterious-function mutations." (PMID 26205529, 2015). "Mutations in the DNAJB6 gene have been identified as rare causes of myofibrillar myopathies." (PMID 33557929, 2021). "Intriguingly, just like BAG3 mutations, mutations in DNAJB6 have been linked to myopathies as well." (PMID 30559338, 2018). "Out of the known list of myofibrillar myopathy–related genes, only the protein quality control related candidates Dnajb6 and Bag3 were significantly up‐regulated in soleus muscle from both hetero‐ and homozygous R405W desmin mice at three months of age." (PMID 41165044, 2025). "The limited knowledge about the substrates of DNAJB6 poses a significant challenge in studying these myopathies." (PMID 41241098, 2025). "This study seeks to further explore the requirement for DNAJB6 in the muscle and improve our understanding of how its disrupted function leads to myopathy." (PMID 38621658, 2024). "Our goal is to accelerate our understanding of mutant DNAJB6 dysfunction in LGMDD1 and thus facilitate therapeutic target identification as well as to gain insight into the relationship between protein quality control and myopathy." (PMID 35931773, 2022). "In any case, the overall expression level of DNAJB6 in skeletal muscle is rather low, which is interesting considering the role of DNAJB6 in myopathy." (PMID 32093037, 2020). "Yet, more research is needed to elucidate the causal relationships between these effects and their importance in the pathogenesis of DNAJB6-related myopathies." (PMID 32093037, 2020). "Studies utilizing in vitro systems and model organisms have revealed functional consequences of disease mutations and offered some insight into the molecular pathomechanism of DNAJB6-related myopathies." (PMID 32093037, 2020).
myopathies (continued). "Muscle imaging revealed that muscles previously considered uninvolved in DNAJB6-myopathy, e.g., lateral gastrocnemii, were affected in patients with new mutations." (PMID 27747217, 2016). "The present review will focus on mutations affecting the chaperone DNAJB6, causing limb-girdle muscular dystrophy type 1D (LGMD1D) and, as shown by recent reports, other forms of myopathy affecting distal muscles." (PMID 27747217, 2016). "Clarification of these issues will provide clues to implement possible therapeutic strategies for DNAJB6-related myopathies." (PMID 27747217, 2016). "The patient with the splicing defect that entirely eliminates DNAJB6's G/F domain (ΔG/F), had severe distal childhood-onset myopathy." (PMID 27747217, 2016). "We detail the mutational, neuropathological, neurophysiological, neurological and radiological features of five new DNAJB6-myopathy families." (PMID 26205529, 2015). "Our patients expand the phenotypic spectrum of DNAJB6-myopathy and allow tentative genotype-phenotype specifications." (PMID 26205529, 2015). "Clinical and imaging examinations reveal that muscles considered uninvolved in DNAJB6-myopathy, e.g. lateral gastrocnemii, are affected in our patients with new mutations." (PMID 26205529, 2015). "For example, mutations in DNAJB6 (homolog of dnj-24) lead to Limb-girdle muscular dystrophy 1E, and mutations in HSPB8 (homolog of hsp-12.2) or BAG2 (homolog of unc-23) were associated with myopathies." (PMID 35733850, 2022). "Mutations in DNAJB6 and DNAJB2 cause myopathy and sensorimotor neuropathy, respectively." (PMID 32093037, 2020). "In this context, the animal models could be useful in preclinical studies addressed to better understand the physio-pathological mechanisms involved in DNAJB6-related myopathies." (PMID 27747217, 2016). "The clarification of these issues and of the molecular mechanisms driven by DNAJB6 protein will provide the knowledge for implementing therapeutic strategies for patients with DNAJB6-related myopathies, as well as for patients with neurodegenerative diseases caused by toxic protein aggregation." (PMID 27747217, 2016). "More recently, the widening of the phenotypic spectrum of DNAJB6-related myopathies was confirmed and a tentative genotype-phenotype correlation was hypothesized." (PMID 27747217, 2016). "Whether this is a coincidence or other DNAJB6-myopathy patients will also develop FTD with aging remains to be seen." (PMID 26205529, 2015). "This family together with our patient with the splicing mutation and the published African-American family delineate the distal myopathy subphenotype of DNAJB6-myopathy and establish tentative genotype–phenotype (proximal versus distal myopathy) correlation in this disease." (PMID 26205529, 2015). "Interestingly, this shows that loss of wildtype DNAJB6 function, rather than a dominant toxic effect, is sufficient to induce myopathy symptoms." (PMID 38621658, 2024). "For example, DNAJB6 [log2 fold-change (log2FC) of 2.24] and the NEF chaperone BAG3 (log2FC of 3.13) lead to Limb-girdle muscular dystrophy 1E58 and myopathies, respectively." (PMID 33846299, 2021). "The reported pathological features in all HSPB8-related myopathies have been similar: dystrophic changes and MFM pathology with protein aggregates (desmin, myotilin, CRYAB, dystrophin, HSPB8, DNAJB6, myotilin, BAG3, TDP-43, and ubiquitin) and rimmed vacuoles." (PMID 32093037, 2020). "For example, based on their impact on muscular ultrastructure or their involvement in myopathies, molecular chaperones, such as TRIC (cct), αB-crystallin/HSPB5 (hsp-25), and DNAJB6 (dnj-24), were suggested to play a key role in sarcomere assembly and maintenance." (PMID 25988162, 2014).
myopathies (continued). "Nevertheless, in the absence of a clear mammalian substrate for DNAJB6, these findings with its closest yeast homolog Sis1 and the impact of the LGMDD1 mutants on client processing provide crucial mechanistic insight to begin to explore therapeutic routes for this myopathy." (PMID 35931773, 2022).